GOLGA4 (golgin A4)
Description:
Involved in vesicular trafficking at the Golgi apparatus level. May play a role in delivery of transport vesicles containing GPI-linked proteins from the trans-Golgi network through its interaction with MACF1. Involved in endosome-to-Golgi trafficking.
Synonyms: golgin-245; GOLG; GCP2; p230; golgin-240; CRPF46; MU-RMS-40.18
Tractability: Small molecule: a structure with a bound ligand is known. Antibody: its Gene Ontology location is reachable by antibodies, with high confidence; UniProt places it where antibodies can reach, with medium confidence. PROTAC: ubiquitination databases record sites on it; its protein half-life has been measured.
Gene: Protein-coding gene on chromosome 3 (37,243,184 to 37,366,879, forward strand). Ensembl gene ENSG00000144674.
Subcellular location: Cytoplasm; Golgi apparatus membrane; Golgi apparatus, trans-Golgi network membrane
Subcellular location (Human Protein Atlas): Golgi apparatus; Nucleoplasm
Pathways (Reactome):
Disease: Signaling by membrane-tethered fusions of PDGFRA or PDGFRB
Vesicle-mediated transport: Retrograde transport at the Trans-Golgi-Network
Gene Ontology:
Molecular function: GTPase binding; protein binding; small GTPase binding
Biological process: Golgi to plasma membrane protein transport; positive regulation of axon extension; Golgi vesicle transport; vesicle-mediated transport
Cellular component: cytoplasm; extracellular exosome; Golgi apparatus; Golgi membrane; cytosol; plasma membrane; trans-Golgi network
Genetic constraint (gnomAD): Loss-of-function variants: 115 observed, 192.1 expected, observed/expected ratio (o/e) 0.6, 90% interval 0.51 to 0.7. The upper end of that interval is the gene's LOEUF score, 0.7, which puts it in group 2 of 6, group 1 being the genes least tolerant of losing a copy. Missense variants: 1,971 observed, 2,067.2 expected, observed/expected ratio (o/e) 0.95, 90% interval 0.92 to 0.99. Synonymous variants: 763 observed, 735 expected, observed/expected ratio (o/e) 1.04, 90% interval 0.98 to 1.1.
Homologues: Orthologues: chimpanzee GOLGA4 (98% identical), macaque GOLGA4 (97% identical), pig GOLGA4 (85% identical), dog GOLGA4 (84% identical), guinea pig GOLGA4 (80% identical), rabbit GOLGA4 (75% identical), mouse Golga4 (71% identical), rat Golga4 (69% identical), tropical clawed frog golga4 (46% identical), zebrafish golga4 (40% identical), Drosophila melanogaster Golgin245 (16% identical).
Diseases named in the same sentence as GOLGA4 in open-access papers:
GOLGA4 is named in the same sentence as 17 diseases in open-access papers, as found by Europe PMC text mining. Sharing a sentence is not in itself a finding about the gene and the disease. The quoted sentences say what the papers report.
breast carcinoma (2 papers, 2020 to 2023). "Next, we measured the relative levels of RBM4 and GOLGA4 variants in clinical breast cancer specimens." (PMID 37415951, 2023). "AURKA regulated pan-breast cancer-associated RNA splicing events including GOLGA4, RBM4 and UBQLN1." (PMID 37415951, 2023). "Moreover, GOLGA4 can be abnormally spliced into GOLGA4-FL isoform in both breast cancer cell lines and clinical breast cancer specimens, suggesting that aberrant splicing of GOLGA4 has an intimate association with breast cancer progression." (PMID 37415951, 2023). "We first selected series of breast cancer cells to measure the relative levels of RBM4 and GOLGA4 variants, for the purpose of exploiting the effect of the RBM4 and GOLGA4 splicing switch on tumor biology." (PMID 37415951, 2023). "Blocking AURKA nuclear translocation with small molecule chemicals partially reversed the oncogenic splicing of RBM4 and GOLGA4 in breast cancer cells." (PMID 37415951, 2023). "Blocking AURKA nuclear translocation with small molecule drugs partially reversed the oncogenic splicing of RBM4 and GOLGA4 in breast cancer cells." (PMID 37415951, 2023). "All the findings imply that aberrant RNA splicing of RBM4 and GOLGA4 is closely related to breast cancer progression." (PMID 37415951, 2023). "Constitutional genes with increased breast cancer relapse risk were claudin 15, WDFY2, golgin A4, DOCK4 while HCG27 and PLAC8L1 were among 18 signature signs not endorsed by prognostic index score." (PMID 33106505, 2020). "The PSI value of GOLGA4 was significantly higher in breast cancer cells than in MCF-10A group." (PMID 37415951, 2023). "RT-PCR was conducted to examine YBX1 and hnRNPK implicated in RNA splicing regulation by virtue of AURKA mediation, which showed that YBX1 knockdown promoted GOLGA4 exon skipping, whereas hnRNPK knockdown promoted RBM4 exon inclusion in breast cancer cells." (PMID 37415951, 2023). "Aberrant splicing of GOLGA4 and RBM4 was closely related to breast cancer development." (PMID 37415951, 2023).
melanoma (2 papers, 2020 to 2021). A malignant, usually aggressive tumor composed of atypical, neoplastic melanocytes. "One report described a melanoma with GOLGA4 fused to exons 8–17 of RAF1, retaining the RAF1 kinase domains, and with accompanying mutations in CTNNB1 and CDKN2A." (PMID 32123303, 2020). "A whole-genome study of 183 melanomas found RAF1 fusions in two melanomas (with partners CDH3 and GOLGA4): one triple wild type and one with an NF1 comutation." (PMID 32123303, 2020).
bipolar disorder (1 paper, 2018). A disorder of the brain that causes unusual shifts in mood, energy, activity levels and the ability to carry out day-to-day tasks. "Golga4 also contained two PAE-specific DMRs across hypothalamic development, and is overexpressed in the prefrontal cortex of individuals with bipolar disorder." (PMID 30568673, 2018).
Sjögren’s syndrome (1 paper, 2021). "GOLGA4 (Golgin-245): Like Golgin-97, Golgin-245 too was identified as an autoantigen in patients with Sjögren’s syndrome." (PMID 34943782, 2021).
tumor (1 paper, 2023). "Three tumor-associated candidates (RBM4, GOLGA4 and UBQLN1) were selected to validate the RNA-seq data." (PMID 37415951, 2023). "By contrast, the PSI value of GOLGA4 was higher in tumor tissue than in normal tissue." (PMID 37415951, 2023). "Nevertheless, the regulatory effects of the two isoforms of GOLGA4 on tumor initiation and progression have not been clearly confirmed." (PMID 37415951, 2023).
GOLGA4 also shares sentences with these, for which no sentence is quoted: Chronic Myeloid Leukemia (5 papers); cancer (2); acute lymphoblastic leukemia (1); cervical cancer (1); chronic neutrophilic leukemia (1); hereditary spastic paraplegia (1); Kawasaki disease (1); leukemia (1); male infertility (1); Parkinson disease (1); Thrombocytosis (1); viral infection (1).